UCHL1 (ubiquitin C-terminal hydrolase L1)
Diseases named in the same sentence as UCHL1 in open-access papers (continued):
Sharing a sentence is not in itself a finding about the gene and the disease.
breast carcinoma (59 papers, 2004 to 2026). "A significant association has been identified between high UCHL1 expression and poor prognosis in ER + breast cancer patients receiving Tamoxifen treatment." (PMID 38468288, 2024). "IMP-1710 serves as a high quality and currently commercially available chemical probe to study UCHL1 not only within a breast cancer context, but also wherever UCHL1 has been implicated in a disease or any mechanistic studies." (PMID 34497382, 2022). "UCHL1 is also associated with many types of cancers including lung, colorectal, breast cancer, and pancreatic, which can promote tumor progression." (PMID 35203526, 2022). "In contrast, UCHL1 expression has been also shown to be associated with increased apoptosis in breast cancer cells." (PMID 19857250, 2009). "It was shown that the level of UCHL1 expression determined in tumor tissue by the immunohistochemical method was associated with an unfavorable outcome in patients with LC and breast cancer, and that this protein could serve as a target for targeted therapy." (PMID 39940785, 2025). "Current understanding of UCHL1’s role is in debate, and previous study suggests that UCHL1 regulates estrogen receptor (ER) and transforming growth factor beta (TGF-β) pathways, and UCHL1 dysregulation is associated with development of breast cancer aggressiveness." (PMID 37815895, 2023). "Moreover, survival analysis of the effect of UCHL1 expression in ER+ breast cancer patients with tamoxifen treatment indicated that high expression of UCHL1 was significantly associated with poor prognosis in patients with breast cancer." (PMID 34497382, 2022). "Furthermore, UCHL1 methylation was positively associated with worse overall survival rates, which is consistent with former studies in breast cancer, esophageal squamous cell carcinoma, and renal cell carcinoma." (PMID 26550574, 2015). "In breast cancer, urothelial bladder cancer, lung cancer, uterine serous carcinoma and glioma, UCHL1 functions as an oncogene." (PMID 41584043, 2026). "Previous studies have reported that 6RK73 suppresses oncogenic UCHL1 activation in breast cancer and delays the progression of renal cell carcinoma (RCC) associated with Xp11.2 translocation/TFE3 gene fusion, particularly PRCC-TFE3 tRCC7." (PMID 41584043, 2026). "Specifically, in NSCLC it was found that UCHL1 promoted pemetrexed-based chemotherapy resistance via the upregulation of thymidylate synthase and in breast cancer drove doxorubicin resistance through the stimulation of free-fatty acid production." (PMID 40078282, 2025). "Among these DUBs, Ubiquitin carboxyl-terminal hydrolase L1 (UCHL1) has garnered attention due to its elevated expression levels in triple-negative breast cancer (TNBC) when compared to other breast cancer subtypes such as Luminal A, Luminal B, and HER2+." (PMID 38468288, 2024). "The expression of UCHL1 in basal-type (mainly TNBC) breast cancer tissue is significantly higher than that in normal breast tissue and adjacent normal tissue." (PMID 38468288, 2024). "Multiple significant studies have highlighted the emerging and crucial roles of UCHL1 in breast cancer." (PMID 38706893, 2024). "UCHL1, Ubiquitin C-Terminal Hydrolase L1, which has been extensively studied in tumors such as lung and breast cancer as well as colorectal cancer, plays a catalytic role in colorectal cancer." (PMID 37168510, 2023). "These tools will enable novel insights into oncogenic mechanisms driven by UCHL1, and identification of substrate proteins deubiquitinated by UCHL1, with the ultimate goal of realising the potential of UCHL1 as a drug target in breast cancer." (PMID 34497382, 2022). "Further experiments will therefore be required to identify the potential of combination strategies with UCHL1 inhibitors for the treatment of ER− breast cancer and TNBC patients." (PMID 34497382, 2022).
breast carcinoma (continued). "The potential role for UCHL1 in promoting breast cancer invasion and metastasis was further supported in a murine breast cancer xenograft model, where UCHL1 overexpressing groups exhibited increased metastasis compared to UCHL1 knockdown groups." (PMID 34497382, 2022). "IMP-1710 and 3 both potently engaged UCHL1 in a breast cancer cell line (Cal51) stably expressing FLAG-tagged UCHL1 within cell EC50 values of 110 and 820 nM, respectively." (PMID 34497382, 2022). "UCHL1 gain-of-function has been connected to the genesis of various types of tumor, including breast cancer, ovarian cancer, and lymphoma; hence, UCHL1 is regarded as an oncogene." (PMID 35463782, 2022). "In summary, the ATM/ZEB1/USP7/CHK1, miR-200c/LINC02582/USP7/CHK1, USP7/PHF8, UCHL3/RAD51, USP52/ASF1A, and UCHL1/HIF-1 signaling axis are potential targets to improve the radiosensitivity of breast cancer." (PMID 34575114, 2021). "Since HIF-1 induces vascular metastasis of breast cancer cells to the lungs, the UCHL1–HIF-1 axis promotes distant tumor metastasis, especially under hypoxic conditions." (PMID 34575114, 2021). "UCHL1 inhibition offers a novel treatment for breast cancer patients with ERα shortage and decrease." (PMID 34575114, 2021). "As a result, AKT–USP4, TRAF4–USP15, and UCHL1 promote breast cancer invasion and metastasis mediated by the TGF-β pathway." (PMID 34575114, 2021). "UCHL1 expression level correlates with poor prognosis of patients with breast cancer, indicating UCHL1 as a prognostic marker and therapeutic target." (PMID 34575114, 2021). "UCHL1 has been reported a potential oncoprotein in colorectal cancer, breast cancer, and uterine serous cancer." (PMID 34398824, 2021). "In several tumor types (e.g. esophageal, hepatocellular and breast cancers), low UCHL1 expression has reportedly been attributed to promoter hypermethylation." (PMID 30359286, 2018). "AKT and ERK1/2 was positively regulated by UCHL1 in B cells, gastric cancer cells and breast cancer cells." (PMID 30359286, 2018). "To validate our results in human tumours, we first performed an immunohistochemical analysis on human breast cancers using anti-UCHL1 and anti-HIF-1α antibodies." (PMID 25615526, 2015). "We confirmed that the expression levels of UCHL1 positively correlated with lower overall survival and distant metastasis-free survival rates in human breast cancer, lung cancer and melanoma." (PMID 25615526, 2015). "UCHL1 is generally found expressed at higher levels in basal-like tumors than the other breast cancer subtypes." (PMID 23506684, 2013). "Here, we report that UCHL1 is frequently methylated in breast cancer cell lines and primary tumors, but rarely in normal breast tissues and mammary epithelial cells, well correlated with its downregulation or silencing." (PMID 22279545, 2012). "Western blot confirmed UCHL1 expression in protein level in breast cancer cell lines, consistent with mRNA level." (PMID 22279545, 2012). "In the present study, we analyzed the epigenetic alteration of UCHL1, its tumor suppressive functions and related-mechanisms in breast cancer." (PMID 22279545, 2012). "Although high expression of UCHL1 was reported to predict early recurrence in patients with invasive breast cancer, other evidences indicated the potential of UCHL1 as tumor suppressor in breast cancer." (PMID 22279545, 2012). "In breast cancer, we found that the promoter methylation of UCHL1 was a promising marker indicative of breast cancer progression." (PMID 22279545, 2012). "Promoter methylation of UCHL1 was detected in 9 of 10 breast cancer cell lines (90%) and 53 of 66 (80%) primary tumors, but rarely in normal breast tissues, which was statistically correlated with advanced clinical stage and progesterone receptor status." (PMID 22279545, 2012). "Next, we evaluated the apoptotic effect of UCHL1 in breast cancer cells using TUNEL and annexin V-FITC/PI staining assays." (PMID 22279545, 2012).
breast carcinoma (continued). "UCHL1 expression was frequently downregulated or silenced in breast cancer cell lines, but broadly expressed in all the normal adult tissues and mammary epithelial cell lines, while USP10 is widely expressed in both normal tissues and breast cancer cell lines." (PMID 22279545, 2012). "We found that UCHL1 was frequently downregulated or silenced in breast cancer cell lines and tumor tissues, but readily expressed in normal breast tissues and mammary epithelial cells." (PMID 22279545, 2012). "Promoter methylation of UCHL1 is significantly correlated with pathologic stage of breast cancer and progesterone receptor status." (PMID 22279545, 2012). "Other cancers with high UCHL1 expression include breast cancer, melanoma, and osteosarcoma." (PMID 40428124, 2025). "Extensive studies of the functions of UCHL1 have shown that the increased expression of this protein contributes to the progression and metastasis of many types of cancer, including gastric cancer, breast cancer, and lung cancer." (PMID 39940785, 2025). "Finally, the group demonstrated in breast cancer cells that inhibition of the PPP perturbed UCHL1 mediated radioresistance." (PMID 40078282, 2025). "UCHL1 may promote doxorubicin (DOX) resistance in breast cancer (BC) by upregulating free fatty acid synthesis, as evidenced by reduced expression of FFA synthase and restored DOX sensitivity following UCHL1 inhibition." (PMID 39944823, 2025). "UCHL1 may promote Doxorubicin resistance in breast cancer by upregulating the synthesis of free fatty acids." (PMID 39944823, 2025). "Similarly, in gallbladder and breast cancer, UCHL1 exhibits overexpression due to promoter hypomethylation and correlates with metastasis and reduced overall survival." (PMID 39236081, 2024). "Demethylation treatment increased UCHL1 expression in breast cancer cell lines." (PMID 38468288, 2024). "Extensive evidence has shown that UCHL1, a key member of the Ub C‐terminal hydrolases subfamily, plays important roles in nervous system disorders, as well as several types of cancer, including nasopharyngeal carcinoma, lung cancer, and breast cancer." (PMID 39223923, 2024). "Besides UCHL1, some other DUBs, such as ATXN3L, BAP1, and USP3 can deubiquitinate KLF5 and are implicated in the pathological development of breast cancer." (PMID 38468288, 2024). "In specific types of breast cancer, high UCHL1 activity may be targeted to enhance the efficacy of endocrine therapy in estrogen receptor-negative breast cancer cells and slow migration and metastasis of triple-negative breast cancer." (PMID 36968845, 2023). "Besides, UCHL1 has also been shown to have tumor suppressive effects in prostate cancer and breast cancer in other studies." (PMID 37815895, 2023). "Growing evidence demonstrates that high UCHL1 activity in specific classes of breast cancers, including ER− breast cancer and TNBC, can be targeted to enhance the efficacy of endocrine therapy in ER− breast cancer cells, as well as to mitigate TNBC migration and metastasis." (PMID 34497382, 2022). "In breast cancer, the expression level of UCHL1 was negatively correlated with estrogen receptor, and inhibition of UCHL1 could enhance the sensitivity to endocrine therapy." (PMID 35756487, 2022). "Moreover, 6RK73 exhibited a similar inhibitory effect on breast cancer extravasation when compared with UCHL1 genetic knockdown." (PMID 34497382, 2022). "A combination of anti-estrogen therapy (such as tamoxifen or fulvestrant) and a UCHL1 inhibitor could be a potential therapeutic strategy for ER- breast cancer, hormone-resistant breast cancers and TNBC patients." (PMID 34497382, 2022). "While a comprehensive mechanism for the correlation between UCHL1 expression and overall survival of TNBC patients remains to be elucidated, UCHL1 could be a biomarker for breast cancer outcome or treatment decisions, particularly in ER− and TNBC." (PMID 34497382, 2022).
breast carcinoma (continued). "Analysis of UCHL1 and ERα expression in patient-derived breast cancer samples showed that UCHL1 expression was significantly higher in TNBC compared to Luminal A, Luminal B and HER2+, suggesting an association between UCHL1 expression and absence or loss of ER expression." (PMID 34497382, 2022). "The underlying mechanism of UCHL1 mediated MDR to P-glycoprotein (P-gp) substrate drugs and the increased invasion and migration in resistant breast cancer cells compared to the sensitive phenotype, which might be associated with MAPK/Erk pathway activation." (PMID 36233276, 2022). "In contrast, it has been known for some time that UCHL1 mRNA level inversely correlates with ER expression level and is highly associated with the recurrence and invasion in breast cancer patients, although a causal relationship was lacking." (PMID 34497382, 2022). "By the same token, cancers that are sensitive to UCHL1 inhibition, but in which the phenotypic outcome or mechanism of action is postulated to be orthogonal to breast cancer, could also benefit from studies using IMP-1710 as a selective and potent probe." (PMID 34497382, 2022). "Role of UCHL1 in promoting breast cancer progression has been well documented." (PMID 35626050, 2022). "Furthermore, UCHL1 activates the Akt pathways to promote the progression of osteosarcoma and breast cancer." (PMID 34257568, 2021). "Moreover, the UCHL1/HIF-1 axis plays an important role in promoting breast cancer resistance to radiotherapy." (PMID 34575114, 2021). "Several studies reported that UCHL1 is a key regulator of the invasion and metastasis of several tumors, including pancreatic neuroendocrine tumors, pediatric high-grade glioma, breast carcinoma, and ovarian cancer." (PMID 34257568, 2021). "UCHL1 has variable roles in cancers, depending on histotype: for instance, the expression of UCHL1 correlates with poor prognosis in patients with multiple myeloma, mammary carcinoma, and pulmonary carcinoma, but has tumor suppressive properties in nasopharyngeal and prostatic carcinoma." (PMID 32211332, 2020). "Moreover, another ubiquitin-protein UCHL1 was reported to promote uterine serous cancer cell proliferation, cell cycle progression, and TGFβ-induced breast cancer metastasis." (PMID 33050659, 2020). "Furthermore, overexpression of UCHL1 is consistent with a multi-drug resistance (MDR) phenotype in breast cancer cells and is believed to function through EGFR and MAPK29,30." (PMID 30914750, 2019). "A thorough proteomic investigation could be useful in identifying novel UCHL1 targets that promote HER2+ breast cancer metastasis." (PMID 30914750, 2019). "Silencing of UCHL1 by promoter methylation in breast cancer indicated that UCHL1 might be a functional tumor suppressor in breast tumorigenesis." (PMID 22279545, 2012). "We next investigated whether promoter CpG methylation was responsible for the silencing of UCHL1 in breast cancer." (PMID 22279545, 2012). "We further investigated the effects of UCHL1 on cell cycle and apoptosis of breast cancer cells." (PMID 22279545, 2012). "Finally, public breast cancer database analyses demonstrated that ITGB4 correlates with PTPRZ1 and that high expression of ITGB4, UCHL1, HIF1A, and PTPRZ1 associated with decreased overall survival, distant metastasis free survival, post progression survival, and relapse-free survival." (PMID 39518121, 2024). "Although EMT may be induced by diverse factors including differential expression of microRNAs, TGF-β, Notch or Wnt signalling, as well as factors in the tumour microenvironment such as hypoxia, only TGF-β and hypoxia signalling have been explored to date for the role of UCHL1 in breast cancer." (PMID 34497382, 2022).
breast carcinoma (continued). "On the other hand, high expression of UCHL1 was found to be inversely correlated with survival rate, in which UCHL1 deubiquitinated the epidermal growth factor receptor, thus suppressing ERα gene transcription, leading to resistance to anti-estrogen therapy in treating breast cancer." (PMID 35884607, 2022). "Interestingly, UCHL1 is also upregulated in other cells under specialized conditions, for example in fibroblasts during wound healing and in pancreatic, colorectal, medullary thyroid, and breast cancer cells." (PMID 32656641, 2020). "The luciferase assay using a deubiquitinating activity-deficient mutant of UCHL1 (C90S mutant) demonstrated that the ubiquitination activity of UCHL1 was essential to stabilize the ODD-fusion protein and upregulated HIF-1 activity in breast cancer-derived EMT6 cells." (PMID 28761052, 2017). "As UCHL1, OTUD5 demonstrated oncogenic roles in colon cancer and breast cancer, and suppressing features in HCC and cervical cancer." (PMID 38918720, 2024). "This dual regulatory capacity of UCHL1, affecting both the mRNA and protein levels of EGFR, distinguishes UCHL1 from other DUBs in the context of breast cancer." (PMID 38468288, 2024). "Together, our data demonstrates the importance and critical roles of UCHL1 and PTPRZ1 in promoting the integrin α6β4-driven invasive phenotype of breast cancer cells." (PMID 39518121, 2024). "In particular, UCHL1 promotes TGF-β signal transduction by acting on the TGF-β signaling pathway and Smad2 signaling pathway, thus inducing breast cancer cell metastasis." (PMID 35546675, 2022). "In several systems, including a zebrafish xenograft model, the authors provide evidence that exosomes enriched in UCHL1 upregulated TGF-β signalling in receptor cells via transfer from exosomes, facilitating migration and extravasation of breast cancer cells." (PMID 34497382, 2022). "Chromatin immunoprecipitation (ChIP) assays showed that UCHL1 knockdown enhanced recruitment of ER to promoter regions of Nuclear Receptor Interacting Protein (NRIP1) and CCND1 genes in ER− breast cancer cells treated with estrogen." (PMID 34497382, 2022). "We next used a complementary murine model of pulmonary metastasis, in which the stable transfectants of the murine breast cancer cells, EMT6, with the UCHL1 expression vector or its empty vector were transplanted orthotopically into the mammary fat pad." (PMID 25615526, 2015). "Several reports demonstrated that the ubiquitin C terminal hydrolase-L1 (UCH-L1) has been found to be an oncogene in malignant tumors such as esophageal carcinoma, lung cancer and breast cancer." (PMID 20677552, 2010). "We further tested the relationship between ErbB-2 expression and the expression of UCHL1, CPS1 and copine III in a panel of breast cancer cell lines." (PMID 14710226, 2004). "Mainly USP4, USP7, USP22, UCHL1, UCHL5, and OTUB1 could be used as biomarkers for each type of cancer such as EOC, breast cancer, melanoma, cervical cancer, and colorectal cancer." (PMID 37107644, 2023). "Consequently, UCHL1 may serve as disease biomarker as well as a potential novel therapeutic target for breast cancers with loss or reduction of ER expression; however, it may not be a suitable target for HER2+ breast cancers, which typically have low endogenous UCHL1 expression." (PMID 34497382, 2022). "For instance, IMP-1710 could be useful to study the role of UCHL1 in other cancer contexts where UCHL1 is known to regulate EGFR expression, such as in EGFR+ colorectal cancers, drug-resistant breast cancer and thyroid and glioma carcinomas." (PMID 34497382, 2022).